GIP (gastric inhibitory polypeptide)
Diseases named in the same sentence as GIP in open-access papers (continued):
Sharing a sentence is not in itself a finding about the gene and the disease.
type 2 diabetes (continued). "Tirzepatide is a dual-acting GIP and GLP-1 agonist with a higher affinity for GIP receptors and is highly effective in not just maintaining a normal glycemic state but also for weight loss in type 2 diabetes mellitus (T2DM)." (PMID 37265914, 2023). "Moreover, GIP and GLP-1 dual agonists are successful pharmacology therapies for type 2 diabetes treatment, employed to promote BW loss." (PMID 37242282, 2023). "Exogenous GIP increased plasma glucagon responses to a mixed meal in individuals with type 2 diabetes and apparently led to a transient worsening of plasma glucose excursions, despite some (limited) evidence of insulinotropic activity during the early phase after meal ingestion." (PMID 37430117, 2023). "However, clinical studies clearly demonstrated that GIP insensitivity in type 2 diabetes mellitus is surmountable, suggesting potential for additive antidiabetic benefits of GIP alongside GLP‐1 in humans." (PMID 33822370, 2022). "Thus, further investigation with longer-term evaluation using our GIP-/- mice is required for elucidating the beneficial effects of GIP for consequential prevention of type 2 diabetes mellitus." (PMID 35909510, 2022). "Importantly, the elevated levels of GIP have been reported in diet-induced obese mice as well as patients with type 2 diabetes." (PMID 33631211, 2021). "Although a dual GIP and GLP-1 receptor agonist has shown efficacy for glucose control and weight loss in clinical trials of patients with type 2 diabetes, it is not clear how much of the observed effect is specifically attributable to GIP agonism." (PMID 34505161, 2021). "GLP-1 agonism is an established pharmacological target for treating type 2 diabetes and obesity, however it is unclear whether pharmacological GIP agonism represents a similar therapeutic opportunity." (PMID 34505161, 2021). "However, recentexciting clinical findings with a dual-acting GLP-1 and GIP receptor hybridpeptide exhibiting strong bias towards the GIP receptor, suggests that GIP resistance in type 2 diabetes is surmountable." (PMID 34588834, 2021). "The physiological importance of islet-derived GLP-1 and GIP in insulin secretion has been previously studied, where their contribution to the regulation of β-cell mass is debated in the pathophysiology of type 1 and type 2 diabetes (T1&T2DM)." (PMID 32090124, 2020). "The insulinotropic properties of GIP make it an attractive prospect for treating type 2 diabetes." (PMID 30466162, 2019). "This may imply that overweight/obese men, similarly to patients with type 2 diabetes, have reduced beta cell sensitivity to GIP." (PMID 31443356, 2019). "This may have detrimental effects on postprandial glucose tolerance as exogenous GIP infusion increased postprandial plasma glucose concentrations in type 2 diabetes patients." (PMID 31443356, 2019). "Taken together, this suggests that GIP may have some utility in the treatment of type 2 diabetes when combined with GLP-1." (PMID 31330984, 2019). "In addition, incretin enthusiasts had suffered a serious disappointment, when it was observed, at about the same time, that GIP although being potently insulinotropic in healthy individuals was ineffective in patients with type 2 diabetes." (PMID 31080438, 2019). "The genetic variability of GIP gene is associated with CAD and it may play a role in the premature CAD in the Chinese Han population with type 2 diabetes." (PMID 29765988, 2018). "Combined with GLP-1, GIP has been proposed as a treatment strategy for type 2 diabetes mellitus." (PMID 29641447, 2018). "However, normalisation of blood glucose levels, as clearly demonstrated in both (DAla2)GIP- and (DAla2)GIP/xenin-8-Gln-treated mice, has also been shown to independently restore GIP insulin-secretory function in type 2 diabetes." (PMID 28004148, 2017).
type 2 diabetes (continued). "RYGB is found in some studies to cause a reduction in postprandial GIP secretion due to the restriction of nutrient passage through the duodenum and jejunum, and this effect may be enhanced in patients with type 2 diabetes mellitus (T2DM)." (PMID 28780756, 2017). "Therefore, further studies are required to systematically assess the direct and indirect beneficial effects of (DAla2)GIP/xenin-8-Gln in restoring GIP action in type 2 diabetes." (PMID 28004148, 2017). "Indeed, impaired insulin secretory effectiveness of GIP is now recognised as a specific and important pathophysiological characteristic of type 2 diabetes." (PMID 27032106, 2016). "Furthermore, GIP levels were more strongly elevated in MR than FR in both type 2 diabetes and controls." (PMID 26704625, 2016). "In type 2 diabetes there is a well characterised global defect of beta-cell insulin secretory capacity that extends to all insulin secretagogoues including glucose, and particularly GIP." (PMID 27032106, 2016). "GIP-based therapy for diabetes was abandoned because the insulinotropic effect of GIP is reduced and GIP-dependent postprandial glucagon production is increased in type 2 diabetes." (PMID 27483245, 2016). "Enhanced glucagon secretion by GIP has been confirmed in patients with type 2 diabetes." (PMID 27483245, 2016). "Given that GIP has a bi-directional glucose-dependent effect on glucagon secretion and has been reported to have a stabilising effect on glycaemia in patients with type 2 diabetes, exogenous GIP could potentially reduce glycaemic variability in this cohort." (PMID 25613747, 2015). "It is worth mentioning that the GIP level in patients suffering from type 2 diabetes is similar to the one in healthy people, however, for unknown reasons, it does not influence blood glucose and insulin level." (PMID 22462016, 2012). "The physiological role of GIP in insulin release and fat metabolism combined with the fact that there is a reduction in the incretin effect in type 2 diabetes makes GIP and its receptor suitable candidate genes for genetic association studies in type 2 diabetes." (PMID 20673334, 2010). "Moreover, normalization of glycemia improves β-cell sensitivity to GIP in diabetic rats and in patients with type 2 diabetes." (PMID 20231880, 2010). "Tirzepatide is a dual glucagon-like peptide-1 (GLP-1) and glucose-dependent insulinotropic polypeptide (GIP) receptor agonist that enhances glucose-dependent insulin secretion, suppresses glucagon, and slows gastric emptying, making it highly effective for weight loss and type 2 diabetes management." (PMID 41368024, 2025). "The remaining 18 MS-PAVs were novel and included proteins that may be inaccessible to affinity-based proteomics, such as a variant in the incretin pro-peptide (Gastric Inhibitory Polypeptide, GIP) which plays a central role in type 2 diabetes and cardiovascular disease pathologies." (PMID 38307861, 2024). "It has been shown that in patients with type 2 diabetes mellitus (T2DM) the response to the incretin effect is altered as a result of a severe defect in the sensitivity for GIP in the β cells and a reduction in food-induced GLP-1 secretion." (PMID 34819089, 2021). "In addition, another study reported that insulinotropic effects of GIP were not impaired by exposure to slightly supra-physiological concentrations of GIP in healthy subjects and age- gender- and weight-matched patients with type 2 diabetes and first-degree relatives of such patients." (PMID 32098413, 2020). "However, considering that GIP acts glucagonotropically in patients with type 2 diabetes the GIP component of dual incretin receptor agonists might counteract GLP-1-mediated inhibition of glucagon secretion, leading to a neutral effect on glucagon levels." (PMID 31443356, 2019). "However, it is evident that this stable GIP/xenin hybrid may represent an attractive potential new therapeutic for type 2 diabetes." (PMID 28004148, 2017).
type 2 diabetes (continued). "In this study, our aim was to evaluate whether or not rs46522 close to GIP was associated with CAD risk in the Chinese subjects with type 2 diabetes." (PMID 28840129, 2017). "While metformin is first-line treatment for type 2 diabetes mellitus, glucagon-like peptide-1 (GLP-1) receptor agonists and glucose-dependent insulinotropic polypeptide (GIP) and GLP-1 dual receptor agonists are frequent add-on agents." (PMID 42164410, 2026). "Overall, 4.5% of participants reported using a GLP-1 or GLP-1/GIP medication in the past year for any reason; 2.9% reported using them to support weight loss, with 1.7% using them exclusively for weight loss (i.e. not also for type 2 diabetes or heart disease)." (PMID 41501776, 2026). "Tirzepatide is a novel dual glucose-dependent insulinotropic polypeptide (GIP) and glucagon-like peptide-1 (GLP-1) receptor agonist approved for the treatment of type 2 diabetes mellitus and chronic weight management." (PMID 41425685, 2025). "A newer dual glucose-dependent insulinotropic peptide (GIP) and GLP-1 receptor agonist, tirzepatide, is also approved for treating type 2 diabetes mellitus." (PMID 40941750, 2025). "In 2023, the advent of glucose-dependent insulinotropic polypeptide (GIP)/GLP-1 receptor agonist tripeptide, which activates both the GIP and GLP-1 receptors, marked another milestone in type 2 diabetes management in Japan." (PMID 40607140, 2025). "While bone turnover markers were not available in this case, referenced studies report that both GIP and GLP-1 receptor agonists can stimulate parathyroid hormone (PTH) secretion in individuals with type 2 diabetes." (PMID 40911613, 2025). "Retatrutide significantly improved glycemic control and substantially reduced body weight in individuals with type 2 diabetes, with a safety profile aligned with that of GLP-1 receptor agonists and combined GIP and GLP-1 receptor agonists." (PMID 40004572, 2025). "Tirzepatide, a dual glucose-dependent insulinotropic peptide/glucagon-like peptide 1 (GIP/GLP1) receptor agonist, was recently approved for type 2 diabetes and weight management." (PMID 40302276, 2025). "Tirzepatide is a glucose-dependent insulinotropic polypeptide (GIP) and glucagon-like peptide-1 (GLP-1) receptor agonist used in the management of type 2 diabetes mellitus." (PMID 41416326, 2025). "In type 2 diabetes, the incretin effect diminishes because of impaired GLP-1 secretion and decreased GIP activity." (PMID 40869064, 2025). "Tirzepatide is a once-weekly subcutaneous injectable peptide engineered from the native GIP sequence, with agonist activity at both the GIP and GLP-1 receptors, and it has been approved for type 2 diabetes." (PMID 39203917, 2024). "Although both GIP and GLP-1 stimulate insulin secretion, their effects differ in type 2 diabetes mellitus (T2DM)." (PMID 39479116, 2024). "Tirzepatide (LY3298176), a novel once-weekly subcutaneous dual GIP and GLP-1 receptor agonist, was originally authorized for treating type 2 diabetes." (PMID 38850440, 2024). "Despite the fact that the GIP hormone was the first insulin-stimulating factor discovered in the 1960s, it demonstrated an impaired insulinotropic effect in patients with type 2 diabetes mellitus (T2DM), disappointing incretin enthusiasts." (PMID 39496023, 2024). "Incretin hormones (glucose-dependent insulinotropic polypeptide [GIP] and glucagon-like peptide-1 [GLP-1]) play a role in the pathophysiology of type 2 diabetes." (PMID 37430117, 2023). "Tirzepatide is a state-of-the-art investigational dual agonist for the glucose-dependent insulinotropic polypeptide (GIP) and glucagon-like peptide-1 (GLP-1) receptors, tailored specifically for treating type 2 diabetes." (PMID 37894644, 2023). "Efficacy and safety of a novel dual GIP and GLP-1 receptor agonist tirzepatide in patients with type 2 diabetes (SURPASS-1): a double-blind, randomised, phase 3 trial." (PMID 37908927, 2023).
type 2 diabetes (continued). "Impaired action or a 50% drop in incretin hormones, glucose-dependent insulinotropic polypeptide (GIP), and GLP-1 have also been reported to result in the decline of β-cell function in type 2 diabetes." (PMID 37109458, 2023). "As the first approved dual agonist of the GIP and GLP-1 receptors on the market, tirzepatide is considered to be a promising drug against type 2 diabetes and obesity." (PMID 37096236, 2023). "Tirzepatide, a glucose-dependent insulinotropic peptide (GIP) and human glucagon-like peptide-1 (GLP-1) receptor agonist, was recently approved to treat type 2 diabetes." (PMID 37096236, 2023). "The main finding when studying the secretion and action of incretin hormones (glucose-dependent insulinotropic polypeptide [GIP] and GLP-1) in individuals with type 2 diabetes is a reduced incretin effect." (PMID 37430117, 2023). "With the glucose-dependent insulinotropic polypeptide (GIP), GLP-1 is an important incretin and GLP-1 agonists are widely used in the management of type 2 diabetes mellitus." (PMID 37466202, 2023). "Tirzepatide (a GIP/GLP-1 receptor co-agonist), for example, reduces HbA1c and body weight in individuals with type 2 diabetes more effectively than selective GLP-1 receptor agonists (e.g. semaglutide)." (PMID 37430117, 2023). "The insulinotropic effect of GIP and GLP-1 is additive in healthy humans but is impaired in people with type 2 diabetes." (PMID 37209227, 2023). "Another potential explanation for the differential reduction in insulinotropic potency of GIP (much impaired) and GLP-1 (mildly reduced) in type 2 diabetes is that GLP-1 can activate the G proteins Gaq and Gas, whereas GIP can only activate Gas." (PMID 37430117, 2023). "Several pharmaceutical methods have been developed to treat Type 2 diabetes by focusing on the development of oral DPP-IV inhibitors to block the degradation of the incretin hormones GLP-1 and GIP." (PMID 37133312, 2023). "Dipeptidyl peptidase-4 (DPP-4) inhibitors which increases GLP-1 and gastric inhibitory polypeptide (GIP) incretin hormone concentrations and GLP-1 receptor (GLP-1R) agonists are now widely used to treat type 2 diabetes and obesity." (PMID 36296337, 2022). "Another pathway to control type II diabetes is through the inhibition of DPP-IV, the enzyme that degrades incretin hormones including GLP-1 (glucagon-like peptide-1) and GIP (gastric inhibitory peptide)." (PMID 36496713, 2022). "This association remained significant in a multivariable model after adjustment for all parameters which significantly correlated with GIP levels (BMI, CRP and type 2 diabetes) (p = 0.0311)." (PMID 35123462, 2022). "DPP4 has been known to regulate glucose metabolism by inactivation of GIP; both GLP-1 and DPP4 inhibitors have been used for type 2 diabetes mellitus (DM) treatment." (PMID 35251476, 2022). "In this review, we present the nephroprotective properties of dual GIP and GLP-1 receptor agonists as a new drug to treat type 2 diabetes." (PMID 36289848, 2022). "Specific DPP-IV inhibitors (gliptins) are currently used in patients with type 2 diabetes mellitus to promote insulin secretion by prolonging the activity of the incretins glucagon-like peptide 1 (GLP-1) and glucose-dependent insulinotropic polypeptide (GIP)." (PMID 35565202, 2022). "Herein, we overviewed the role of GIP and GLP-1 in the pathophysiology of type 2 diabetes and systematically reviewed the efficacy and safety of injectable incretin-based therapy added to basal insulin in light of the results of the SURPASS-5 trial." (PMID 36157450, 2022). "Meta-analysis of cardiovascular secondary outcomes from the SURPASS program, testing efficacy of a new novel dual GIP/GLP-1 receptor agonist tirzepatide, demonstrates cardiovascular safety in patients with type 2 diabetes." (PMID 35210595, 2022). "Recently, a dual GIP and GLP-1 receptor agonist has been approved for the treatment of type 2 diabetes." (PMID 36289848, 2022).
type 2 diabetes (continued). "In fact, comparing GLP-1 alone administration, the co-infusion resulted in similar blood glucose and insulin secretion rates in type 2 diabetes, but the suppression of plasma glucagon by GLP-1 was antagonized by GIP." (PMID 35054422, 2021). "DPP-4 inhibitors are commonly used to treat type 2 diabetes, because they enhance circulating levels of incretins, such as glucagon-like peptide-1 (GLP-1) and glucose-dependent insulinotropic polypeptide (GIP), to enhance insulin secretion." (PMID 31969650, 2020). "In patients with type 2 diabetes (T2DM), an impaired insulin response to GLP-1 and GIP contributes to hyperglycemia." (PMID 32308645, 2020). "Glucagon-like peptide-1 (GLP-1) and glucose-dependent insulinotropic polypeptide (GIP) are important regulators of metabolism, making their receptors (GLP-1R and GIPR) attractive targets in the treatment of type 2 diabetes mellitus (T2DM)." (PMID 31330984, 2019). "Type 2 diabetes patients have dysfunction in incretin hormones (as glucagon-like peptide-1 or GLP-1, and glucose-dependent insulinotropic polypeptide or GIP)." (PMID 23697612, 2013). "Sitagliptin, a highly selective DPP IV inhibitor, is currently used in the treatment of type 2 diabetes patients to improve glucose tolerance by increasing the half-life of GLP-1 and glucose-dependent insulinotropic peptide (GIP)." (PMID 23621921, 2013). "Vilsboll and coworkers showed that a normal GIP secretion, but reduced postprandial concentrations of biologically active GLP-1 in type 2 diabetic patients." (PMID 23590862, 2013). "Since GIP has also been shown to exert β-cell prosurvival and adipocyte lipogenic effects in rodents, both GIP receptor agonists and antagonists have been considered as potential therapeutics in type 2 diabetes (T2DM)." (PMID 22802954, 2012). "The glucose-dependent insulinotropic polypeptide (GIP) and the glucagon-like peptide-1 (GLP-1) receptors are considered complementary therapeutic targets for type 2 diabetes." (PMID 21935440, 2011). "The incretin hormone glucose-dependent insulinotropic polypeptide (GIP) was not initially adopted as a therapeutic because it loses glucose-lowering efficacy in type 2 diabetes." (PMID 41174263, 2026). "Clinical studies have reported elevated GIP levels in the gingival crevicular fluid (GCF) of periodontitis patients with type 2 diabetes as well as in obese periodontitis patients without diabetes." (PMID 41596254, 2026). "However, the secretion and function of GIP are impaired in individuals with type 2 diabetes mellitus (T2DM), and the regulatory mechanisms governing GIP secretion remain unclear." (PMID 40012909, 2025). "DPP4 inhibitors, also known as “gliptins”, have been added to treatment regimens of type 2 diabetes, as they strongly reduce DPP4-mediated inactivation of the incretin hormones glucagon like peptide-1 (GLP-1) and gastric inhibitory polypeptide (GIP) and thus lower blood glucose levels." (PMID 40817204, 2025). "Tirzepatide, marketed under the brand name Mounjaro, is a dual glucose-dependent insulinotropic polypeptide (GIP) and glucagon-like peptide-1 (GLP-1) receptor agonist that was authorized for use in type 2 diabetes in May 2022." (PMID 41416326, 2025). "We measured plasma levels of SCGN and GIP in both fasting and postprandial states among nondiabetic healthy individuals and patients with type 2 diabetes." (PMID 40012909, 2025). "Tirzepatide, a dual glucose-dependent insulinotropic polypeptide (GIP) and glucagon-like peptide-1 (GLP-1) receptor agonist, produces substantial weight loss and glycaemic improvement in people with and without type 2 diabetes mellitus (T2DM)." (PMID 41211573, 2025). "Plasma concentrations of GIP are normal or elevated in individuals with type 2 diabetes, while meal-induced serum levels of GLP-1 are slightly but significantly reduced in patients with impaired glucose tolerance and those with type 2 diabetes." (PMID 40649920, 2025).